USP31 (ubiquitin specific peptidase 31)
Description:
Deubiquitinase that recognizes and hydrolyzes the peptide bond at the C-terminal Gly of ubiquitin. May play a role in the regulation of NF-kappa-B signaling pathway by deubiquitinating TRAF2. (Microbial infection) Plays a positive role in foot-and-mouth disease and classical swine fever viral infection. Mechanistically, associates with internal ribosomal entry site (IRES) element within the 5'-untranslated region of viral genomes to promote translation of the virus-encoded polyprotein.
Synonyms: KIAA1203
Tractability: PROTAC: ubiquitination databases record sites on it.
Gene: Protein-coding gene on chromosome 16 (23,061,406 to 23,149,452, reverse strand). Ensembl gene ENSG00000103404.
Subcellular location (Human Protein Atlas): Cytosol
Gene Ontology:
Molecular function: cysteine-type deubiquitinase activity; cysteine-type peptidase activity; ubiquitin-like protein peptidase activity
Biological process: protein deubiquitination
Cellular component: nucleus
Genetic constraint (gnomAD): Loss-of-function variants: 43 observed, 114.09 expected, observed/expected ratio (o/e) 0.38, 90% interval 0.29 to 0.49. The upper end of that interval is the gene's LOEUF score, 0.49, which puts it in group 2 of 6, group 1 being the genes least tolerant of losing a copy. Missense variants: 1,640 observed, 1,672.1 expected, observed/expected ratio (o/e) 0.98, 90% interval 0.94 to 1.02. Synonymous variants: 749 observed, 676.74 expected, observed/expected ratio (o/e) 1.11, 90% interval 1.04 to 1.18.
Homologues: Orthologues: chimpanzee USP31 (99% identical), macaque USP31 (98% identical), dog USP31 (93% identical), rat Usp31 (92% identical), mouse Usp31 (91% identical), pig USP31 (90% identical), rabbit USP31 (88% identical), guinea pig USP31 (78% identical), tropical clawed frog usp31 (61% identical), zebrafish usp31 (58% identical). Paralogues in human: USP43 (31% identical), USP19 (17% identical), USP24 (17% identical), USP4 (16% identical), USP15 (15% identical), USP9X (15% identical), USP32 (15% identical), USP11 (14% identical), USP9Y (14% identical), USP6 (13% identical), USP36 (13% identical), USP34 (13% identical), and 59 more.
Diseases named in the same sentence as USP31 in open-access papers:
USP31 is named in the same sentence as 18 diseases in open-access papers, as found by Europe PMC text mining. Sharing a sentence is not in itself a finding about the gene and the disease. The quoted sentences say what the papers report.
deafness (3 papers, 2012 to 2021). An inherited or acquired condition characterized by the complete loss of the ability to hear from one or both ears. "A second USP31 SNP, Chr6.25714052, was also associated with adult-onset deafness in our cohort, although this locus had the lowest odds ratio of the three candidate loci." (PMID 23028339, 2012). "USP31 and RBBP6 have been shown to be strongly associated with late onset deafness in border collies." (PMID 26664958, 2015).
breast carcinoma (2 papers, 2015 to 2021). "Aberrant protein degradation may be important in this cancer, as three of the 14 mutated genes (USP4, USP31, and ZNRF4) in the breast cancer are involved in the ubiquitin–proteasome pathway." (PMID 26432421, 2015).
atrial fibrillation (1 paper, 2024). A disorder characterized by an electrocardiographic finding of a supraventricular arrhythmia characterized by the replacement of consistent P waves by rapid oscillations or fibrillatory waves that vary in size, shape and timing and are accompanied by an irregular ventricular response. "Of all 19,605 quantified genes, the largest increase in ΔREC in LSD was exhibited by Usp31 (ΔREC = 2411%), a potential biomarker for clear cell renal cell carcinoma and Syt11 (ΔREC = 1517%), known for its role in atrial fibrillation." (PMID 38534766, 2024). "There is no information to date about the role of Usp31 in cardiac pathophysiology, but Syt11 was reported to decrease the risk of atrial fibrillation." (PMID 38534766, 2024).
Endometrial adenocarcinoma (1 paper, 2023). "Moreover, immunohistology from the HPA database revealed the diversity of protein expressions of USP31 in endometrium and EC (Endometrium, patient id 3333; Endometrial adenocarcinoma, patient id: 2122)." (PMID 36508192, 2023).
larynx carcinomas (1 paper, 2011). A primary or metastatic malignant neoplasm involving the larynx. "Moreover, USP31 was highly expressed in 8 out of 27 larynx carcinomas (30%), and only in 2 out of 31 normal tissues, where its expression was restricted to the proliferative basal layer (data not shown)." (PMID 21283576, 2011).
microcephaly, primary autosomal recessive 1 (1 paper, 2024). "Mcph1 (microcephaly, primary autosomal recessive 1; REC-N = 39.05) was the most controlled gene in “N”, while Usp31 (ubiquitin specific peptidase 31, REC-L = 27.93) and Syt11 (synaptotagmin XI, REC-L = 26.25) were the most controlled genes in “L”." (PMID 38534766, 2024).
Oral leukoplakia (1 paper, 2026). A thickened white patch on the oral mucosa that cannot be rubbed off. "Fine-mapping revealed 14 coding variants, such as a missense variant in USP31 for caries and in MANBA for oral leukoplakia, and a stop-gained variant in GPNMB for temporomandibular disorders." (PMID 42310951, 2026).
Parkinson disease (1 paper, 2012). A progressive degenerative disorder of the central nervous system characterized by loss of dopamine producing neurons in the substantia nigra and the presence of Lewy bodies in the substantia nigra and locus coeruleus. "USP31 is a ubiquitin-related gene that has been linked to Parkinson's disease in humans." (PMID 23028339, 2012).
sarcoma (1 paper, 2021). A usually aggressive malignant neoplasm of the soft tissue or bone. "ENTPD2, the most stably expressed gene in “A” is a biomarker for lung and hepatocellular carcinomas, while USP31, the most variably expressed gene in “A”, could be a potential target for sarcomas." (PMID 34209090, 2021).
soft tissue sarcoma (1 paper, 2025). A malignant neoplasm arising from muscle tissue, adipose tissue, blood vessels, fibrous tissue, or other supportive tissues excluding the bones. "In soft tissue sarcoma, YAP inhibits the expression of ubiquitin specific peptidase 31 (USP31), a key upstream negative regulator of NF-κB, thereby diminishing its inhibitory effect on NF-κB activity." (PMID 40673277, 2025).
viral infection (1 paper, 2025). "Although USP31 has been associated with cellular stress responses and immune signaling pathways relevant to viral infection, our findings indicate that it does not directly influence DENV-IRES-driven translation." (PMID 41472110, 2025).
cancer (6 papers, 2011 to 2024). A tumor composed of atypical neoplastic, often pleomorphic cells that invade other tissues. "As RUNX1 can bind to USP31, to further investigate the interaction by searching for inhibitors against both by Genomics of Drug Sensitibity in Cancer (GDSC)." (PMID 38886545, 2024). "In Luminal B, USP31 is involved in immune regulation, particularly in the modulation of the NF-κB pathway, which is frequently dysregulated in cancer." (PMID 39596229, 2024). "Several TILs were negatively correlated with USP31 expression in many human cancers." (PMID 36508192, 2023).
tumor (5 papers, 2012 to 2025). "EC patients with low USP31 expression had worse postoperative prognosis, which was associated with many important pathways in tumor." (PMID 36508192, 2023). "USP31, a member of the large cysteine protease family of deubiquitinating enzymes, localizes to post-synaptic lipid rafts and has been implicated in the regulation of NF-kB signaling and tumor progression." (PMID 41472110, 2025). "The high recurrence of genes like C1QBP and RPS3A in Luminal A, USP31 and RRM1 in Luminal B, and PSMD8 and YME1L1 in Basal subtypes highlights the subtype-specific regulatory networks that underlie tumor progression." (PMID 39596229, 2024). "Contrary to other tumours, where USP31 is shown to act as a tumour suppressor, its inhibition by PLB in HCC showed reduced cancer progression." (PMID 39275349, 2024). "There are only a few studies on USP31, but all of them confirmed the importance of USP31 in tumor progression." (PMID 36508192, 2023). "The transcriptional orientation of the MMTV genome relative to the transcriptional orientation of the gene in which it integrated, was determined for four genes (Usp31, Nckap5, Cadm2 and Notch4) for which there was available tumor RNA." (PMID 23131872, 2012). "By stabilizing key components of this pathway, USP31 may enhance immune evasion and contribute to the tumor’s ability to escape immune surveillance." (PMID 39596229, 2024). "However, it is noteworthy that some studies have started to focus on the role of USP31 in tumor progression." (PMID 36508192, 2023). "This suggested that USP31 may play a suppressor role in tumor progression." (PMID 36508192, 2023). "Inhibition of USP31 via PLB makes GPX4 available for protein degradation, followed by tumour cell apoptosis." (PMID 39275349, 2024).
kidney (1 paper, 2025). "Recent studies have identified two eukaryotic proteins that have received attention as potential host factors for viral IRESs: polycystic kidney disease 1-like 3 (PKD1L3) and ubiquitin-specific peptidase 31 (USP31)." (PMID 41472110, 2025).
kidney disease (1 paper, 2022). "We found that polycystic kidney disease 1-like 3 (PKD1L3) and ubiquitin-specific peptidase 31 (USP31) were associated with FMDV-IRES activity." (PMID 35468926, 2022).
USP31 also shares sentences with these, for which no sentence is quoted: Adult onset (2 papers); clear cell renal cell carcinoma (1); endometrial cancer (1).